TRPM8 (transient receptor potential cation channel subfamily M member 8)
Description:
Non-selective ion channel permeable to monovalent and divalent cations, including Na(+), K(+), and Ca(2+), with higher permeability for Ca(2+). Activated by multiple factors, such as temperature, voltage, pressure, and changes in osmolality. Activated by cool temperatures (<23-28 degrees Celsius) and by chemical ligands evoking a sensation of coolness, such as menthol and icilin therefore plays a central role in the detection of environmental cold temperatures. TRPM8 is a voltage-dependent channel; its activation by cold or chemical ligands shifts its voltage thresholds towards physiological membrane potentials, leading to the opening of the channel. In addition to its critical role in temperature sensing, regulates basal tear secretion by sensing evaporation-induced cooling and changes in osmolality (By similarity). May play a role in prostate cancer cell migration. [Isoform 2]: Negatively regulates menthol- and cold-induced channel activity by stabilizing the closed state of the channel. [Isoform 3]: Negatively regulates menthol- and cold-induced channel activity by stabilizing the closed state of the channel.
Synonyms: LTrpC-6; LTrpC6; Trp-p8; TRPP8
Tractability: Small molecule: an approved drug acts on it; a structure with a bound ligand is known; a high-quality ligand is known; it belongs to a druggable protein family. Antibody: UniProt places it where antibodies can reach, with high confidence; its Gene Ontology location is reachable by antibodies, with high confidence; UniProt predicts a signal peptide or a membrane-spanning region. PROTAC: a small molecule that binds it is known.
Target class: Voltage-gated ion channel; Ion channel; Transient receptor potential channel
Chemical probes: CHEMBL2443061, PF-05105679 (high quality), RQ-00203078
Gene: Protein-coding gene on chromosome 2 (233,917,373 to 234,019,522, forward strand). Ensembl gene ENSG00000144481.
Subcellular location: Cell membrane; Membrane raft; Endoplasmic reticulum membrane
Pathways (Reactome):
Transport of small molecules: TRP channels
Gene Ontology:
Molecular function: protein binding; calcium channel activity; ligand-gated calcium channel activity; calcium ion transmembrane transporter activity; identical protein binding; monoatomic ion channel activity
Biological process: calcium ion transmembrane transport; positive regulation of cold-induced thermogenesis; thermoception; calcium-mediated signaling; response to cold
Cellular component: endoplasmic reticulum membrane; plasma membrane; membrane raft; external side of plasma membrane; membrane; plasma membrane raft
Genetic constraint (gnomAD): Loss-of-function variants: 86 observed, 108.92 expected, observed/expected ratio (o/e) 0.79, 90% interval 0.66 to 0.94. The upper end of that interval is the gene's LOEUF score, 0.94, which puts it in group 4 of 6, group 1 being the genes least tolerant of losing a copy. Missense variants: 1,174 observed, 1,324.3 expected, observed/expected ratio (o/e) 0.89, 90% interval 0.84 to 0.93. Synonymous variants: 502 observed, 523.65 expected, observed/expected ratio (o/e) 0.96, 90% interval 0.89 to 1.03.
Homologues: Orthologues: chimpanzee TRPM8 (99% identical), macaque TRPM8 (99% identical), pig TRPM8 (96% identical), dog TRPM8 (96% identical), guinea pig TRPM8 (94% identical), mouse Trpm8 (94% identical), rat Trpm8 (94% identical), rabbit TRPM8 (92% identical), tropical clawed frog trpm8 (76% identical), tropical clawed frog trpm8 (64% identical), Drosophila melanogaster Trpm (27% identical), Caenorhabditis elegans gon-2 (26% identical), and 4 more. Paralogues in human: TRPM2 (42% identical), TRPM4 (32% identical), TRPM5 (32% identical), TRPM3 (29% identical), TRPM1 (28% identical), TRPM7 (26% identical), TRPM6 (26% identical).
Diseases named in the same sentence as TRPM8 in open-access papers:
TRPM8 is named in the same sentence as 162 diseases in open-access papers, as found by Europe PMC text mining. Sharing a sentence is not in itself a finding about the gene and the disease. The quoted sentences say what the papers report.
prostate carcinoma (113 papers, 2008 to 2026). A carcinoma that arises from epithelial cells of the prostate gland. "TRPM8 is associated with tumor development, for example, prostate cancer, colon cancer, and squamous cell carcinoma." (PMID 38893478, 2024). "A combination of genes circulating mRNA signature (GOLM1, NKX3-1 and TRPM8) was able to identify high-risk prostate cancer cases (85% of sensitivity and 58% of specificity)." (PMID 37091783, 2023). "This loss of interaction and delocalization of TRPM8 outside of lipid rafts, significantly increases prostate cancer cell motility." (PMID 37576340, 2023). "For example, TRPM8, which has been proved as a marker for high‐risk prostate cancer and was detected overrepresented in blood plasma, had a TPM of 0.065 in plasma and 30.0 in seminal plasma." (PMID 35858042, 2022). "TRPM8 is overexpressed in prostate cancer and its expression level is associated with cancer cell death." (PMID 35919815, 2022). "We show that TRPM8 and Rap1 N17 interact in intact prostate cancer cells, validating docking analyses since the point mutation of Y32 in the Rap1 sequence significantly weakened the intracellular interaction with TRPM8 (Figure 5bii)." (PMID 35565390, 2022). "Here, we have characterized and investigated the effects of TRPM8 modulators in prostate cancer aggressiveness disclosing the molecular mechanism underlying their biological activity." (PMID 34853378, 2021). "Prominently, testosterone shows high colocalization with TRPM8 channels in human prostate tissues and co-immunoprecipitation experiments using prostate cancer cells have revealed that testosterone is associated with TRPM8 localized in the plasma membrane." (PMID 32471309, 2020). "There is debating evidence obtained from the prostate cancer and human kidney cells, that TRPM8 channel activation is associated with production of oxidative stress." (PMID 30858386, 2019). "TRPM8 function is also linked to cell survival in prostate cancer and TRMP8 suppression lead to oxidative stress and apoptosis." (PMID 29772843, 2018). "Since androgens are significantly implicated in prostate cancer development, the role of the novel testosterone receptor TRPM8 in cancer was assessed in our study." (PMID 28039451, 2017). "Our recent findings indicated that the hallmark Ca2+ channel of the prostate epithelium TRPM8 undergoes targeted degradation in the prostate cancer cell line, LNCaP." (PMID 28039451, 2017). "On the other hand, the anti-tumor effect of ectopically expressing TRPM8 in AR- prostate cancer xenograft is associated with decreased tumor neovascularization." (PMID 26512697, 2015). "Overexpression of TRPM8 in prostate cancer cells might position TRPM8 mRNA levels as a promising diagnostic marker, as they have shown diagnostic advantages in comparison to other biomarkers." (PMID 35976012, 2022). "Nevertheless, because of their distribution in metastatic sites (lung or liver), LNC–WS12s could be used to target metastasis dissemination in patients with prostate cancer before anti–androgenic therapy and the subsequent loss of TRPM8 expression." (PMID 35743115, 2022). "TRPM8 encodes a receptor‐activated non‐selective cation channel involved in detection of sensations such as coolness that also plays a role in prostate cancer cell migration whereas SPP2 is involved in retinitis pigmentosa in humans and its function is to respond to elevated platelet cytosolic Ca2+." (PMID 34096632, 2021). "Moreover, several studies have involved TRPM8 as a key player in cancer cell migration, and the transition to the androgen-independent aggressive stage of prostate cancer has been shown to positively correlate with loss of TRPM8 expression." (PMID 31888223, 2019). "Another TRPM8 activator, WS-12, may be used as a diagnostic marker for prostate cancer by incorporating radiohalogens." (PMID 29772843, 2018). "TRPM8 has been originally identified as a cancer-associated gene in prostate carcinoma." (PMID 29221175, 2017).
prostate carcinoma (continued). "It has already been well established that TRPM8 is increased in age-associated malignancies such as colon and prostate cancer but whether expression of TRPM8 is increased purely as a result of aging has yet to be established." (PMID 24593692, 2014). "TRPM8 might be a useful marker for prostate cancer outcome, since loss of TRPM8 expression appears to be associated to transition to androgen independence and poor prognosis." (PMID 23251635, 2012). "Taken together, these studies suggest that TRPV2 and TRPM8 (along with NKX3.1) may constitute a valuable immunohistochemical panel to diagnose prostate cancer, and may identify patients at risk of aggressive disease who need early therapeutic intervention (as opposed to watchful waiting)." (PMID 37240443, 2023). "This regulatory role of TRPM8 is disrupted during prostate cancer development caused by the intense protein degradation that might lead to diminished rates of rapid Ca2+ intake, and simultaneously, uncoupled testosterone levels in the absence of its high-affinity receptor." (PMID 28039451, 2017). "This TRPM8-mediated inflammation promotes NK cell infiltration, thereby enhancing antitumor immunity activity in prostate cancer." (PMID 41601666, 2026). "Recently, there has been increased interest in TRP channels, which are overexpressed and dysregulated in various carcinomas, such as TRPC3 in ovarian cancer, TRPC6 in hepatocellular carcinoma, TRPM7 in breast cancer and TRPM8 in prostate cancer." (PMID 40813985, 2025). "Also, WS-12, another TRPM8 activator, could be utilized as a prostate cancer diagnostic marker." (PMID 40813985, 2025). "Other prostate cancer-associated somatic mutations were consistent in some PDOs and parental tumours, such as BRCA1, ALK, STED2, TET2, TRPM8, AURKA, ERBB2, GATA2." (PMID 41403018, 2025). "Curcumin, a polyphenol derived from Curcuma longa, has been shown to modulate TRPM8 channels, thereby inhibiting prostate cancer cell proliferation and inducing cell cycle arrest." (PMID 40813985, 2025). "Here, we report a comparative analysis of the cation channel transient receptor potential melastatin 8 (TRPM8; also known as transient receptor potential cation channel subfamily M member 8) in lung, breast, colorectal, and prostate cancers." (PMID 40405392, 2025). "Another observation supporting an association between TRPM8 functionality and etoposide sensitivity is that in other cytostatic-sensitive tumor cells, TRPM8 remains overexpressed in prostate cancer cells." (PMID 38339011, 2024). "Initially isolated from prostate cancer cells, TRPM8 channels were primarily investigated in relation to prostate cancer, highlighting their protective anti-invasion properties and their potential as diagnostic and prognostic markers." (PMID 39062591, 2024). "In this regard, it is known that TRPM8 is involved in testosterone signaling relevant to prostate cancer." (PMID 39150496, 2024). "For instance, in prostate cancer, TRPM8 expression predicts aggressive behavior with early metastatic disease." (PMID 37240443, 2023). "In another way, the positive effect of TRPM8 antagonists for prostate cancer treatment was demonstrated using the androgen-dependent prostate cancer cells LNCaP." (PMID 37033630, 2023). "In oral, bone, and prostate cancer, TRPM8 upregulates the activity of MMP2 and MMP9, stimulating invasiveness." (PMID 37033630, 2023). "There is contradictory information about the effect of TRPM8 modulation in prostate cancer, as both agonists and antagonists have been shown to decrease proliferation and migration and promote apoptosis in PCa cells in vitro." (PMID 37033630, 2023). "In prostate cancer (PCa) cells, the expression of the TRPM8 channel is controlled by androgens via androgen receptor (AR) activation." (PMID 37033630, 2023).
prostate carcinoma (continued). "In human prostate carcinoma, it was demonstrated that TRPM8 channel activation with TRPM8 agonists promotes apoptosis, an effect mediated by an increase in intracellular Ca2+ concentration." (PMID 37033630, 2023). "The TRPM8 agonist, D3263 (Dendreon, Seal Beach, CA, USA), has already been trialed in a limited number of patients with solid tumors, including advanced prostate cancer." (PMID 37240443, 2023). "TRPM8 channel overexpression or activation promotes tumor growth under hypoxic conditions in prostate cancer, an effect facilitated by the upregulation of HIF-1α protein through Ca2+-dependent inhibition of RACK1." (PMID 37033630, 2023). "Following that, knocking down TRPM8 channels in osteosarcoma and prostate cancer cell lines increased apoptosis induced by epirubicin, suggesting an enhancement in chemosensitivity." (PMID 37033630, 2023). "Inhibition of the ubiquitination cascade increases the activity of the TRPM8 channel in the plasma membrane which has been proposed as a therapeutic strategy for regulating cell growth and proliferation in prostate cancer cells." (PMID 37033630, 2023). "The TRPM8 agonist, D3263 (Dendreon, Seal Beach, CA, USA), was also trialed in a limited number of patients with solid tumors, including advanced prostate cancer." (PMID 37240443, 2023). "Gkika and colleagues conducted a study of TRP channels in prostate cancer, suggesting that TRPM8 and TRPV6 were novel markers for tumor progression." (PMID 37986367, 2023). "The role of TRPM8 channels in prostate cancer is still controversial due to reports showing both pro-proliferative/antiproliferative and pro-apoptotic/anti-apoptotic effects of the channel." (PMID 37033630, 2023). "The use of TRPM8 has a great impact in castration-resistant prostate cancer, which is considered to be the most aggressive form of PCa, because it is usually resistant to androgen deprivation therapy." (PMID 36837490, 2023). "The different subcellular localization presented by our research were also observed at TRPM8 in human prostate cancer cells." (PMID 36790286, 2023). "In prostate cancer, TRPM8 expression shows a strong correlation with grade (ISUP grade 4 or higher) and perineural invasion." (PMID 37240443, 2023). "Notwithstanding, TRPM8 was first identified as a biomarker of prostate cancer, and its pharmacological blockade reduces the proliferation of prostate cancer cells." (PMID 36614186, 2023). "For instance, TRPM8 channels have an important role in the diagnosis, prognosis, and treatment of prostate cancer." (PMID 37033630, 2023). "TRPM8 is a potential early-stage prostate cancer biomarker because it is significantly upregulated in early stages and decreased in advanced stages of prostate tumors." (PMID 36835177, 2023). "High internalization and degradation of TRPM8 correlates with greater severity of human prostate cancer cases." (PMID 36844925, 2022). "In that study, we concluded that TRPM8-driven calcium cytotoxicity synergizes with radio-, chemo- or hormone therapy to establish a lethal condition in prostate cancer cells." (PMID 35204694, 2022). "Although some data suggest a role of the Ca2+-dependent inactivation of the focal-adhesion kinases (FAK), the exact molecular mechanism by which TRPM8 impairs the motility of epithelial prostate cancer cells is still unclear." (PMID 35565390, 2022). "Emerging evidence indicates that the TRPM8 channel plays an important role in prostate cancer (PCa) progression, by impairing the motility of these cancer cells." (PMID 35565390, 2022). "First identified during a screening for upregulated genes in prostate cancer, TRPM8 is subsequently found to be overexpressed in a wide range of cancers such as breast cancer and pancreatic adenocarcinoma." (PMID 35361751, 2022).
prostate carcinoma (continued). "In prostate cancer LNCaP cells, while overexpression of TRPM8 transcript is observed, TRPM8 protein was internalized from its normal plasma membrane localization, ubiquitinated, and degraded via proteasomal and lysosomal pathways." (PMID 36844925, 2022). "In accordance with cell migration data, overexpression of TRPM8 is correlated with a significant decrease in cell adhesion, even in the absence of the agonist, indicating a role of this channel in inhibiting prostate cancer cell adhesion." (PMID 35565390, 2022). "Selective amino-acid-based TRPM8 antagonists are able to inhibit androgen-dependent prostate cancer cell proliferation, migration and invasiveness." (PMID 36613628, 2022). "In recent decades, several lines of evidence have highlighted the key involvement of the TRP channel TRPM8 in prostate cancer." (PMID 35743115, 2022). "At the same time, menthol, a TRPM8 activator, inhibits the proliferation of prostate cancer cell lines." (PMID 35919815, 2022). "D3263 is an orally active, TRPM8 agonist able to slow down tumor progression in advanced prostate cancer patients and in benign prostatic hyperplasia." (PMID 36844925, 2022). "In AR+ prostatic carcinoma cell line LNCaP, silencing TRPM8 or capsazepine blockade of TRPM8 limited cell viability and provoked apoptotic nuclei formation." (PMID 36844925, 2022). "TRPM8 was first identified and cloned from prostate tissue, and showed to be upregulated in prostate cancer." (PMID 35976012, 2022). "Recently, a new TRPM8 isoform was identified in the ER membranes from human prostate cancer cells and keratinocytes, characterized by the presence of four transmembrane domains instead of six (4-TM-TRPM8)." (PMID 36613628, 2022). "In prostate cancer, TRPM8 antagonists, which perturb the androgen-elicited rapid responses, lower intracellular calcium levels and inhibit cell proliferation." (PMID 35875160, 2022). "In this context, among others, we demonstrated the TRPM8 channel to be a major player due to its ability to impair prostate cancer cell motility." (PMID 35565390, 2022). "The anti-metastatic role of TRPM8 in prostate cancer due to its ability to impair PCa cells’ motility has been suggested in recent years." (PMID 35565390, 2022). "A study has showed that TRPM8 over-expressed in advanced prostate cancer, and TRPM8 promoted cancer cell growth in vitro hypoxia, drug resistance, and in vivo tumorigenicity, with increased HIF-1α expression." (PMID 36033489, 2022). "The presence of TRPM8 was shown in the endoplasmic reticulum (ER) of several cell types, including human keratinocytes, bronchial epithelial cells, prostate cancer cells as well as mouse vascular smooth muscle cells." (PMID 35216232, 2022). "In prostate cancer, D-3263 (an orally bioavailable small molecule that targets TRPM8) binds and activates TRPM8, induces Ca2+ to enter cells, causing the destruction of calcium ion homeostasis and cell death of tumor cells expressing TRPM8." (PMID 35813831, 2022). "The important physiological role of TRPM8, as well as its involvement in different pathophysiological conditions (prostate cancer, migraine, obesity, cold pain, itch, inflammation), makes this channel an important target for different studies." (PMID 36555804, 2022). "TCAF2 promotes cell migration in prostate cancer by recruiting TRPM8 to the cell membrane, whereas TCAF1 reduces the speed and migration of these cells." (PMID 36012311, 2022). "In this regard, TRPM8 is a possible prostate cancer biomarker reported to be significantly increased in early-stage prostate cancer, while its expression is significantly decreased in advanced stages androgen-independent prostate tumors." (PMID 34831222, 2021). "TRPM8 antagonists inhibit the androgen-dependent prostate cancer cell proliferation, migration and invasiveness." (PMID 34853378, 2021).